MMP9 (matrix metallopeptidase 9)
Diseases named in the same sentence as MMP9 in open-access papers (continued):
Sharing a sentence is not in itself a finding about the gene and the disease.
cancer (continued). "MMP9 is a gelatinase that degrades type 4 collagen in the basement membrane of cells, creating a microenvironment where cancer cells can invade and metastasize." (PMID 38906916, 2024). "STAT3 promotes EMT, a key factor in cancer metastasis, by reducing E-cadherin and increasing vimentin and MMP9 expression." (PMID 39519023, 2024). "Expectedly, there were significant changes in the expression of growth stimulatory genes in response to MMP‐9 knockdown, and the altered genes were especially enriched with functions that contribute to cell growth and cancer development." (PMID 38600695, 2024). "Matrix metalloproteinase-9 (MMP-9) is involved in cell remodeling in the extracellular matrix, which plays a crucial role in cancer invasion and metastasis." (PMID 38589471, 2024). "Some of the most recent in vitro and in vivo studies investigating the effects of natural and synthetic polyphenols on the expression and activity of MMP-2 and MMP-9 in various cancer models are summarized below." (PMID 39335164, 2024). "Since MMP-9 is associated with cancer invasion and metastasis, regulation of MMP-9 is an important therapeutic approach for combating cancer invasion and metastasis." (PMID 39351229, 2024). "Among the different MMPs, MMP-2 (gelatinase A) and MMP-9 (gelatinase B) are notably significant in cancer metastasis due to their potential to degrade type IV collagen, a primary element of the basement membrane." (PMID 39431222, 2024). "Our study can achieve the functional integration of MMP9 and PD-L1 that influence cancer development through targeting MED1." (PMID 39343952, 2024). "Apoptosis mediated by reactive oxygen species (ROS) can also act on EMT through the PI3K/AKT/NFKB/MMP-9 signalling pathway in cancer." (PMID 38317159, 2024). "Olivacine has the highest affinity for the MMP9 docking pocket, and Olivacine-mediated lysosomal cytosol sputum plays a key role in drug resistance in cancer cells." (PMID 38580922, 2024). "MMP-9 has been identified as a potential cancer biomarker in several cancer types due to its critical role in the invasive potential of tumors." (PMID 38461536, 2024). "MMP-9 regulates cancer cell proliferation and metastasis in part by clearing Wnt/planar cell polarity protein-tyrosine kinase-7 (PTK7)." (PMID 38956273, 2024). "IL6 upregulates MMP2 and MMP9 in OC, which degrades the extracellular matrix and makes passages for tumor invasion and cancer cell metastasis." (PMID 39766086, 2024). "IL-1β has been shown to stimulate the production of MMP-9 and the proto-oncogene tyrosine-protein kinase Src, which heavily encourages cancer metastasis and proliferation." (PMID 39451257, 2024). "Research has unveiled mixed findings regarding MMP9 expression in relation to breast and colon cancer survival rates, indicating its multifaceted impact on cancer outcomes." (PMID 38939095, 2024). "High concentrations of quercetin significantly decreased MMP-2 and MMP-9 expression, while low concentrations increased it, which, in turn, enhanced the malignant potential of cancer cells." (PMID 39335164, 2024). "MMP-2 and MMP-9, members of the matrix metalloproteinase family, play a vital role in various tumors and are considered key regulators of cancer progression." (PMID 38951593, 2024). "Since MMPs are critical modulators of the extracellular environment in cancer and have been shown to often cleave in the vicinity of O‐glycosylation sites, we selected MMP9 to test the modulation of its activity by truncated O‐glycan trees specifically." (PMID 39074261, 2024). "Elevated MMP-9 levels are commonly observed in cancer tissues compared to normal adjacent tissues, promoting cancer cell migration and invasion." (PMID 39075554, 2024). "MMP9, also known as Matrix metalloproteinase-9, is a biomarker gene that has gained attention in the field of cancer research in recent years." (PMID 38560573, 2024).
cancer (continued). "In pan-cancer, both MMP9 and SCGN were associated with a variety of immune regulatory molecules, including chemokines, receptors, MHC molecules, immunosuppressive molecules, and immune activating molecules." (PMID 38375034, 2024). "MMPs, particularly MMP-2 and MMP-9, play crucial roles in cancer metastasis by degrading the extracellular matrix components, which facilitates invasion and further progression." (PMID 39203749, 2024). "The correlation with metastasis is proposed to be influenced by SOX3 positive modulation of matrix metalloproteinase-9 (MMP-9), a key player in cancer cell migration." (PMID 38927713, 2024). "This strategy is expected to be transformed into a new technique for diagnosis of specific cancers related to MMP-9 and assessing the extent of cancer occurrence, development and metastasis." (PMID 38240894, 2024). "For instance, the administration of cinobufacini notably decreases MMP2 and MMP9 levels, thereby inhibiting cancer cell migration and invasion." (PMID 39664453, 2024). "Increased MMP-9 expression and activity have been reported in a range of lung conditions, various cancers, immunopathology in infectious diseases, and more." (PMID 38398037, 2024). "Matrix metalloproteinases (MMP) -2 and MMP-9 are enzymes that break down the extracellular matrix and basement membrane, which are crucial barriers preventing the spread of cancer cells." (PMID 39839762, 2024). "Proteins such as Twist1, Snail, and MMP9 are implicated in the EMT, migration, and invasion of cancer." (PMID 39000112, 2024). "Given the significance of MMP9 gene in cancer, it is being thoroughly studied as a potential therapeutic target." (PMID 38560573, 2024). "In the search for more promising therapies, matrix metalloproteinases have become of significant interest, such as MMP-1, MMP-2, MMP-9, and MMP-13, which have been linked to more aggressive forms of cancer and earlier metastases." (PMID 39063046, 2024). "Among all MMPs, MMP-2 and MMP-9 are key to basement membrane type IV collagen degradation during cancer progression." (PMID 38539165, 2024). "Elevated ECM stiffness activates the FAK/RhoA/ROCK and PI3K/AKT signaling pathways via integrins, thereby increasing the expression of MMP2 and MMP9, and enhancing the invasiveness of cancer cells." (PMID 38693104, 2024). "IL-18 has been shown to upregulate CD44, VEGF, and MMP-9 in an NF-κB-dependent manner, which increases cancer’s metastatic properties." (PMID 39451257, 2024). "Metalloproteinase (MMP-2 and MMP-9) were found to be important signs of cancer return upon analysis of MMP-2 and MMP-9 levels in radical prostatectomy tissues." (PMID 38672151, 2024). "Matrix metalloproteinase 9 (MMP9) redounded to the basement membrane degradation, which was an important basis for the invasion of malignant tumors." (PMID 38438882, 2024). "The increased expression of MMP-9 in various cancer is usually correlated with a poor disease prognosis." (PMID 38342891, 2024). "For instance, MMP-9-mediated degradation of FN alters αvβ6 integrin dynamics, enhancing β6 integrin expression and promoting cancer cell invasion." (PMID 38693104, 2024). "The vital involvement of MMP-9 in extracellular matrix (ECM) remodeling unveils a substantial correlation between MMP-9 and each stage of cancer pathogenesis and progression." (PMID 37569509, 2023). "In this study, the investigators determined that UA treatment resulted in decreased activity of matrix metalloproteinase-9 (MMP-9), an enzyme responsible for basement membrane and extracellular matrix degradation seen in local invasion of cancer cells." (PMID 37637627, 2023). "In this work, we show that treatment with resistin induces an increase in FAK phosphorylation levels and an increase in MMP-2 and MMP-9 secretion in PC3 cancer cells." (PMID 38137922, 2023). "MMP-2 and MMP-9 are upregulated in most cancers and play crucial roles in modulating invasion and metastasis." (PMID 37833873, 2023).
cancer (continued). "The therapeutic effect of AuNPs against the potent proinflammatory mediator MMP-9 was examined on the cancer cells treated by PMA." (PMID 37372062, 2023). "As for MMP9, several other molecules promoting cancer cell proliferation are present inside the NET." (PMID 37444436, 2023). "Mangiferin exhibits numerous beneficial pharmacological properties, including antioxidant, anti-inflammatory, anti-diabetic, anti-cancer, and analgesic effects, and some of these functions come to work by the inhibition of MMP-9." (PMID 37175113, 2023). "Cancer cells can break through the physical barrier of the extracellular matrix by influencing host cells to secrete MMP-9 to degrade multiple collagen proteins in the basement membrane to metastasize and invade other tissues." (PMID 37765183, 2023). "In NSCLC, TAM expressed high levels of MMP-9, which significantly increased cell migration and invasion, participated in vessel formation and sprouting, and thus lead to cancer progression." (PMID 37766868, 2023). "In the TME, neutrophils produce MMP-9 to stimulate angiogenesis, boosting cancer growth and offering extra immune-escape pathways for cancer cells." (PMID 37513975, 2023). "Curcumin decreases reactive oxygen species (ROS) induced by hypoxia, suppresses the expression of HIF-1 in K1 cancer cells, enhances E-cadherin expression, and inhibits MMP-9 activity." (PMID 37175113, 2023). "MMP9 was upregulated, and miR-145 downregulated in cancer tissues, with a median MMP9/miR-145 ratio 17.6-fold higher versus controls." (PMID 38001954, 2023). "In certain cancer types, the significant increase in MMP9 transcription can be observed in parallel with the upregulation of ECM1, suggesting that the ECM1–MMP9 axis is of great significance for tumorigenesis and progression." (PMID 36765767, 2023). "NGAL has the ability to form heterodimers with MMP9, thus preventing MMP9 degradation, and increased NGAL-MMP9 complex formation has been detected in certain cancers." (PMID 37223632, 2023). "Currently, most studies only focus on the roles of MMP-9-activable imaging probes for cancer imaging, and seldom utilized them for intraoperative surgical guidance." (PMID 36978072, 2023). "Malignant tumors’ ability to invade and spread is thought to be aided by MMP-9, which is present in the plasma membrane and its secreted forms." (PMID 37037467, 2023). "As documented in many researches, both MMP‐2 and MMP‐9 proteins are abundantly expressed in different malignancies and these proteins facilitate cancer metastasis." (PMID 38012058, 2023). "The actual activity of MMP-9 was found to be significantly different between both grades of cancer and control tissue." (PMID 36979935, 2023). "In the extracellular matrix, NE and MMP9 remodel laminin, whose cleavage activates the α3β1 integrin, which triggers the proliferation of cancer cells." (PMID 37444436, 2023). "MMP-9, despite its well-established role as a factor promoting the development of cancer, induces the expression of endostatin, which inhibits the formation of new blood vessels." (PMID 37509417, 2023). "The involvement of the gelatinases, such as MMP-2 and MMP-9, with the development and progression of cancer is well documented." (PMID 36961055, 2023). "In CCA etiology, assessment of TNF-α is varied; it promoted cancer cell invasiveness by MMP-9 through the activation of MAPK and ERK1/2 with cancer cell by MMP-9 through the activation of MAPK and ERK1/2 with metabolites FAK and COX-2." (PMID 36768732, 2023). "Meanwhile, the relative expression level of MMP1, MMP3, and MMP9, related to the proliferation of cancer cells in the downstream pathway was significantly decreased." (PMID 37477531, 2023). "Recent literature provides well-established evidence regarding the overexpression of MMP-9 in cancer." (PMID 36938194, 2023). "MMP-9 has become a highly valuable target that is involved in cancer and many other diseases, such as autoimmune and cardiovascular diseases." (PMID 37569509, 2023).
cancer (continued). "Related to this, MMP-9 facilitates transendothelial migration and it is probable that co-regulation of MMP-9 with de-adhesion of cancer cells to the endothelium is integral to the metastatic progression." (PMID 36910158, 2023). "The expression of gelatinases in all examined tissues, determined by Western immunoblot was similar with the exception of MMP-9 in the low-grade cancer tissue of the urinary bladder." (PMID 36979935, 2023). "Although TIMP1 is a natural inhibitor of MMPs involved in the matrix remodeling during carcinogenesis, it converges toward cancer cell survival by binding MMP9/CD44 complex and mediating PI3K/AKT pathway activation." (PMID 36906579, 2023). "We have demonstrated a significant correlation between CXCR2 expression and cancer cell MMP9 in ESCC tissues (p = 0.010) through IHC, and the expression ratio of CXCR2 to CXCR1 was the highest in TE-10 among the three ESCC cell lines on Western blot." (PMID 37296952, 2023). "Conditioned medium from platelet-cancer cell cocultures has previously been shown to have high MMP-9 activity and stimulate cancer cell invasion." (PMID 36806315, 2023). "Cluster 2 (green) was associated with the upstream molecules of MMP and contained 6 terms, including metastasis, mmp, in-vitro, mmp-9, mmp-2, activation, nf-kappa-b, cancer-cells, iv collagenase, receptor." (PMID 36814819, 2023). "In the case of some proteins affected in cancer cases, such as matrix metalloproteinase-9 (MMP-9) and Caspase-3, only flavanones 1a and 1b exhibited a Pa close to 0.7." (PMID 37376079, 2023). "Lacticaseibacillus rhamnosus, Lactobacillus crispatus, Lactobacillus delbrueckii, and Limosilactobacillus reuteri supernatants inhibited cancer cell proliferation, promoted apoptosis, and downregulated the expression of MMP-9 to reduce cancer cell invasion." (PMID 37835359, 2023). "MMP2 and MMP9 have been demonstrated to play critical roles in the degradation of basement membrane collagen, as well as cancer progression and metastasis." (PMID 35871358, 2023). "As a result, controlling and inhibiting MMP-9 is a crucial therapeutic strategy for treating different illnesses, especially cancer." (PMID 37037467, 2023). "TANs, along with regular neutrophils, secrete substantial amounts of matrix metalloproteinase (MMP)-9, which play a role in the degradation of the extracellular matrix and cancer progression." (PMID 38137361, 2023). "Among the factors involved in PNI, matrix metalloproteinases (MMPs), especially MMP‐2 and MMP‐9, are believed to be essential for collagen degradation and drive cancer cells to disseminate along nerves." (PMID 37830980, 2023). "Taken together, we propose a schematic model in which the LCN2/LOXL2/MMP9 complex promotes the migration and invasion of cancer cells through intracellular and extracellular means." (PMID 37753805, 2023). "The proteolytic breakdown of the extracellular matrix components by gelatinases, such as matrix metalloproteinase MMP-2 and MMP-9, is a critical step in cancer development and metastasis." (PMID 37496822, 2023). "In A549 cells, ginsenoside Rh2 (G-Rh2), derived from ginseng, exerts its anti-metastasis activity by repressing MMP-9 expression through miR-491, thereby inhibiting cancer metastasis." (PMID 37766868, 2023). "MMP-9 is a major member of the zinc metalloproteinase family because it stimulates cancer metastasis by degrading ECM and collagens, facilitating cancer cell invasion and metastasis." (PMID 36870981, 2023). "PCNA is essential for DNA replication, and MMP9 is related to cancer cell metastasis, both of which contribute to CRC development." (PMID 37347740, 2023). "There are reports in the fields of ESCC, oral squamous cell, gastric, breast, and bladder carcinomas that suggest MMP9 expression in cancer cells is significantly related to poor clinical outcomes including patient survival or lymph node metastases." (PMID 37296952, 2023).
cancer (continued). "Those cells are exploited by the cancer cells to further release MMP-2 and MMP-9 to degrade the surrounding extracellular matrix (ECM) that cancer cells can reach vasculature." (PMID 35600975, 2023). "Among all MMPs, MMP-9 has been shown to have a critical function in the growth and metastasis of cancer cells." (PMID 36910158, 2023). "Low MMP-9 expression in cancer and stromal cells demonstrates a significantly improved disease-free patient survival compared to patients with higher MMP-9 expression." (PMID 37372062, 2023). "Depending on the structural studies, many MMP-9 inhibitors have been designed to be used in the treatment of cancer." (PMID 36938194, 2023). "Compared with the adjacent normal tissues and cancer tissues of patients taking atorvastatin, the expressions of MMP9, MMP12, CD36, and FABP4 in LUSC tissues increased significantly." (PMID 37978381, 2023). "The purpose of this prospective cohort study was to evaluate the effect of external biliary drainage on enzyme activity of MMP-9 in the serum of patients with malignant hilar biliary obstruction." (PMID 36837539, 2023). "On the other hand, in hormone-independent VCap cells, EGFR, AR, and Matrix Metalloproteinase-9 (MMP-9) are reported to cooperate to promote cancer progression." (PMID 37463954, 2023). "Among the 23 members of the MMP family, MMP-2, MMP7, and MMP-9 are regarded as key factors involved in cancer metastasis." (PMID 37427379, 2023). "MMP9 can degrade various components of the extracellular matrix to promote cancer cell invasion and liberate ligands for growth factor receptors from the extracellular matrix." (PMID 38022584, 2023). "Previous studies have collectively suggested ALA as a potent inhibitor of MMP-2 and MMP-9 activities, which reduces the invasion of various cancer cells." (PMID 37496822, 2023). "MMP9 is a metalloproteinase known to degrade extracellular matrix proteins, which is also known to be a step for cancer cell invasion." (PMID 37268731, 2023). "The FAK/ILK/ERK/PI3K/NFB pathways are activated when FN1 binds to integrin, which causes overexpression of MMP-2 and MMP-9 and the destruction of the extracellular matrix (ECM) as well as the invasion of cancer cells." (PMID 37640804, 2023). "This function is complementary to the enzymatic remodelling of type IV basement membrane collagen by MMP‐2 and MMP‐9, two zinc‐dependent endopeptidases, which thereby are involved in promoting cancer metastasis." (PMID 37581480, 2023). "Based on the effect of A3 on M2-type macrophage polarization, we believe A3-influenced relevant mediators CCL2 and MMP-9 released by macrophages to inhibit angiogenesis and cancer cell migration." (PMID 36838599, 2023). "Our method revealed that direct contact with macrophages stimulated matrix metalloproteinase 9 (MMP9) production in ESCC cells, and that MMP9 played an integral role in cancer cell migration and invasion in vitro." (PMID 37296952, 2023). "Within our total 69 ESCC cases, we obtained 19 cases of MMP9 positive in cancer cells at the invasive front (referred to “cancer cell MMP9” below)." (PMID 37296952, 2023). "Our findings show that cancer cell MMP9 expression is significantly correlated with M2-like macrophage infiltration and poor clinical outcomes in human ESCC tissues on IHC analysis." (PMID 37296952, 2023). "From there, downstream signaling occurs, involving various pathological conditions, including tumorigenesis and insulin resistance, making MMP-9 a viable target for cancer and diabetes therapies." (PMID 36831374, 2023). "In contrast, the direct proteolytic action of MMP-9 leads to cancer spread, most likely via the control of VEGF and angiostatin production and in association with angiogenesis." (PMID 36874130, 2023). "Particularly, NET‐associated neutrophil elastase (NE) and matrix metalloprotease 9 (MMP‐9) cleaved laminin which triggered the proliferation of dormant cancer cells." (PMID 38062888, 2023).